TNF (tumor necrosis factor)
Diseases named in the same sentence as TNF in open-access papers (continued):
Sharing a sentence is not in itself a finding about the gene and the disease.
adenomyosis (20 papers, 2011 to 2025). The growth of endometrial tissue inside the muscular wall of the uterine corpus. "It is induced by TNF-alpha, a key pro-inflammatory cytokine, which has been heavily implicated in adenomyosis pathology." (PMID 40989079, 2025). "The TNF signalling pathway demonstrates more significant enrichment and encompasses a larger number of genes, underscoring its notable contribution to the inflammatory cascades linked to adenomyosis." (PMID 40989079, 2025). "Our analysis revealed significant dysregulation in the TNF signaling pathway and Rap1 signaling pathway, both of which were highly enriched in adenomyosis samples compared to controls." (PMID 40989079, 2025). "Research indicates that TNF-α signalling can stimulate inflammatory processes, leading to the misplaced presence of endometrial tissue, a characteristic feature of adenomyosis." (PMID 40989079, 2025). "The bioinformatic assessment highlighted the TNF and Rap1 signalling pathways as enriched in adenomyosis, emphasizing their roles in disease development." (PMID 40989079, 2025). "In patients with adenomyosis, the expression of several inflammatory cytokines, such as IL-1β, IL-6, IL-8, IL-10, TNF, NF-κB, MCP-1, and RANTES, is abnormal, and a variety of signaling pathways such as TLR437 and MAPK/ERK are involved." (PMID 36230643, 2022). "The Qiu treatment inhibited the expression of IL-1β, IL-6, and TNF-α in the tamoxifen-induced adenomyosis mice in a dose-dependent manner." (PMID 34931128, 2021). "And this activation was related to the elevated levels of IL-1β, IL-6, and TNF-α in serum and uterine tissue of adenomyosis mice." (PMID 34931128, 2021). "The elevated levels of IL-1β, IL-6, and TNF-α in serum and uterus tissues of adenomyosis model mice were also decreased after Qiu treatment." (PMID 34931128, 2021). "Our findings showed that mifepristone significantly decreased the expressions of IL-6 and TNF-α in both endometrial epithelial and stromal cells of adenomyosis, which may be the reason that mifepristone is more effectively than progestins in the relief of adenomyosis-associated pain." (PMID 32038106, 2020). "Inflammatory mediators, including IL-6, TNF-α, IL-1β and IL-10, are involved in inflammatory pathway and contribute to the intense painful symptoms in adenomyosis 8-10." (PMID 32038106, 2020). "In the present study, we found that mifepristone reduces the secretion of IL-6 and TNF-α from endometrial epithelial and stromal cells in adenomyosis." (PMID 32038106, 2020). "Ectopic mononuclear cells of women with adenomyosis produced higher levels of IFNγ, IFNα and TNFα than the mononuclear cells of eutopic endometrium." (PMID 29178922, 2017). "Targeting macrophage-related biomarkers, such as specific cytokines (e.g., TNF-α, IL-6) or macrophage surface markers (e.g., CD68), could provide diagnostic tools or therapeutic targets for adenomyosis." (PMID 40989079, 2025). "Our findings demonstrated that the TNF signaling pathway is the one that most affects adenomyosis." (PMID 40989079, 2025). "The disruption of TNF signalling components in adenomyosis could contribute to the inflammatory environment observed in affected endometrial tissues." (PMID 40989079, 2025). "Even with limited amount of patients, we are able to identify that TBK‐1 and TNF‐α were correlated with dysmenorrhea, which was consistent with a previous study that NF‐κB DNA‐binding activity was correlated with the severity of dysmenorrhea in adenomyosis." (PMID 34010983, 2021). "The cGAS, STING, TANK‐binding kinase 1 (TBK‐1), interferon‐α (IFN‐α), IFN‐β, and tumor necrosis factor‐α (TNF‐α) mRNA and protein levels in the ectopic endometrial tissue from adenomyosis patients were significantly higher compared with that from the controls in endometrium (p < .05)." (PMID 34010983, 2021). "Studies on TNF-α levels in patients with diseases similar to UFs, such as uterine sarcoma or adenomyosis, may open up a new chapter in gynecological diagnostics." (PMID 30518097, 2018).
adenomyosis (continued). "For example, patients with adenomyosis have an increased number of macrophages, gamma delta T cells in ectopic and eutopic endometrium, and elevated preinflammatory factors and cytokines (e.g. TNF-α, IL-10, and IL-18) in the uterus and peritoneal fluid." (PMID 21385399, 2011). "The pathways enriched in the overlapping genes included TNFα signaling via NFKB, estrogen response, RAS-signaling and response to wounding, all also involved in adenomyosis development." (PMID 35563206, 2022). "The systemic and local immune changes have been observed in women affected by adenomyosis, accompanied by the elevated levels of IL-6, IL-1β, IFN-α, TNF-α, and IFN-γ, and the coexistence of changes in inflammatory and anti-inflammatory signals." (PMID 34931128, 2021). "Recent findings suggested that myomatosis and adenomyosis share some pathogenetic features like a state of excess inflammation, increased endothelial nitric oxide synthesis with upregulation of MMP, and inflammatory cytokines such as interleukin-1 and TNF-α." (PMID 24163697, 2013). "Another study has found that tumor necrosis factor-α and vascular endothelial growth factor (VEGF) can stimulate the release of the C-X-C motif chemokine ligand 1 (CXCL1) in endometrial epithelial cells derived from the endometrium of patients with adenomyosis." (PMID 39456936, 2024).
anaphylaxis (20 papers, 2009 to 2026). An acute hypersensitivity reaction that occurs from exposure to an allergen. "Consistently, serum levels of pro-inflammatory cytokines TNF-α and IL-6 were elevated in C48/80-induced anaphylaxis mouse models but were significantly reduced by treatment with DXM." (PMID 34737708, 2021). "Cytokines, such as the tumor necrosis factor-α, interleukin (IL)-4, IL-5, and IL-10, act as the contributing mediators in the development of various anaphylaxis symptoms." (PMID 34169047, 2021). "For instance, in response to cytokines such as Interleukin-1, Interleukin-6, Tumor necrosis factor-α or Interferon-γ (most of them are mediators of anaphylaxis)." (PMID 34248989, 2021). "Activated mast cells in anaphylaxis can express histamine, TNF-α, PAF and VEGF, all of which have been shown to increase vascular permeability by influencing function of AJs." (PMID 34360549, 2021). "The levels of TNF-α and IL-6 in peritoneal fluid decreased in the Ang-1-treated mice anaphylaxis model." (PMID 24586553, 2014). "Also, anti-T20 protected OVA allergic mice from PGN-induced lethal anaphylaxis, and the serum levels of TNF-α, IL-6, and LTC4 of anti-T20 treated PGN-challenged OVA allergic mice were decreased as compared to isotype control of anti-T20 treated mice." (PMID 27213155, 2016). "Newly synthesized TNF-α, which amplifies the allergic symptoms by inducing chemotaxis of neutrophils and other inflammatory cytokine production, plays a critical role in the late phase of an anaphylaxis reaction." (PMID 24586553, 2014). "Similarly, patients with both pyrogenic reactions and anaphylaxis had significantly higher peak concentrations of IL-6, IL-10, TNFα and sTNFRI compared to patients with severe anaphylaxis alone." (PMID 23936562, 2013). "In patients who had anaphylaxis, concentrations of IL-6 and IL-10 remained elevated for up to 24 hours after the initial dose of antivenom, whereas concentrations of TNFα and sTNFRI returned to baseline levels between 10–15 hours after the initial dose of antivenom." (PMID 23936562, 2013). "In addition, TNF‐α signaling may also play a critical role in the development of cefaclor‐induced anaphylaxis." (PMID 40974473, 2025). "Second, our experiment showed the IP IOP administration could decrease the proinflammatory cytokines of TNF and IL-6 and oxidative stress, but includes no data demonstrating the lower risk of anaphylaxis and hypersensitivity." (PMID 37376162, 2023). "In the analysis of systemic anaphylaxis, the body temperature recovered and the concentrations of HIS, TNF-α, and IL-8 in serum were reduced by AT pretreatment." (PMID 35684410, 2022). "In the present study, roxatidine decreased mRNA levels of TNF-α, IL-6, and IL-1β in PMACI-stimulated HMC-1 and the serum of anaphylactic shock animal models." (PMID 28139747, 2017). "Cytokines such as TNFα, endotoxin, shear stress and hypoxemia may contribute to endothelial apoptosis in anaphylaxis and sepsis, but experimental or clinical data are lacking making it difficult to propose any significant pathological role for apoptosis in vascular leakiness." (PMID 34360549, 2021).
aspergillosis (20 papers, 2009 to 2025). Aspergillosis is an infection, growth, or allergic response caused by the Aspergillus fungus. "The cytokines IL-6 and TNF play a key role in anti-Aspergillus immunity with mice deficient in either cytokine possessing an increased susceptibility to Aspergillosis." (PMID 34975870, 2021). "Individuals carrying the T-allele at P268S, which was associated with a reduced susceptibility to aspergillosis in patients, induced significantly lower IL-1β and demonstrated a trend toward lower TNF production in response to Aspergillus stimulation." (PMID 29980664, 2018). "It is important for clinicians to be aware that patients on TNF-α inhibitor therapy are at increased risk of aspergillosis due to the critical role that TNF-α plays in innate protection against A. fumigatus." (PMID 23971044, 2013). "This stands in contrast with previous suggestions that CPA might be associated with low levels of IFN-γ (Doffinger D, AAA2014 Abstract) and that TNF-α might be linked with aspergillosis and/or chronic cavitary pulmonary asergillosis." (PMID 30333797, 2018). "Polymorphisms within the tumor necrosis factor-α (TNF-α) gene and its receptors have also been associated with susceptibility to aspergillosis." (PMID 36602962, 2023). "Administration of TNF-α to immunosuppressed mice in a model for pulmonary aspergillosis increased survival." (PMID 30558125, 2018). "Of the cytokines and chemokines identified by our in vivo studies, TNF-α has been shown to be critical for anti-fungal immunity and is a key cytokine required for neutrophil recruitment in murine models of pulmonary aspergillosis." (PMID 25637383, 2015). "Of the 12 RA patients, four were receiving TNFα antagonist therapy (infliximab, n = 3; etanercept, n = 1) at diagnosis of aspergillosis." (PMID 19886992, 2009). "The four RA patients on TNFα antagonist therapy had severe Aspergillus disease; there were two cases of pulmonary aspergillosis, one case of invasive pulmonary aspergillosis, and one case of intracranial aspergillosis." (PMID 19886992, 2009). "However, the major limitation of using TNF-α in the treatment of aspergillosis is its serious toxicity after systemic administration, including hepatotoxicity, nephrotoxicity, and neurotoxicity." (PMID 30558125, 2018). "Additionally, adiponectin knockout mice have a higher frequency of TNF-α producing alveolar macrophages, which is reduced upon adiponectin supplementation, and increased transcription of IL-1α, IL-6, IL-12β, IL-17, and TNF-α in their lungs during aspergillosis, than wild type mice." (PMID 35273609, 2022). "The interference of Dectin-1 interaction with β-glucans by a soluble dectin-Fc fusion protein dampened the expression of inflammatory cytokines, TNFα, IL-1, IL-6, MIP-2, CCL3, G-CSF, and GM-CSF, expression in vivo, and increased fungal burden during aspergillosis." (PMID 36177012, 2022).
chondrosarcoma (20 papers, 2005 to 2025). A malignant cartilaginous matrix-producing mesenchymal neoplasm arising from the bone and soft tissue. "NUC1 also inhibited the release and protein expression of MMP-1, 3, and 13, in TNF-α-induced chondrosarcoma cells in a concentration-dependent manner." (PMID 37482815, 2023). "This study demonstrated that NUC1 inhibited the production of NO in LPS-induced macrophages, and reduced MMP-1, MMP-3, and MMP-13 levels in chondrosarcoma cells treated with TNF-α." (PMID 37482815, 2023). "While activating PI3K signaling and the administration of TNFα to chondrosarcoma cells and chondrocytes promoted tumor progression and inflammatory responses, those cells paradoxically generated a chondroprotective conditioned medium." (PMID 35804814, 2022). "The present study demonstrated induction of the apoptosis and necroptosis processes in chondrosarcoma SW1353 cells by TNF-α, which were altered by the KP extract." (PMID 33799537, 2021). "In chondrosarcoma cells, tumor necrosis factor (TNF)-α had a stimulatory effect on MMP-9 and insignificant effect on MMP-2 and interleukin (IL)-1β stimulated MMP-9 and MMP-2." (PMID 24085323, 2013). "Here, we show that other genes under NF-κB control, such as IL-6, IL-8, ICAM-1 and Mcp-1, are modulated as well in the HTB-94 chondrosarcoma cell line stimulated with TNFα." (PMID 20113495, 2010). "MMP-3 and MMP-13 gene expression induced by IL-1β, TNF-α and IL-17 was downregulated by mithramycin in human chondrosarcoma SW1353 cells and in primary human and bovine femoral head chondrocytes." (PMID 15987479, 2005). "Meanwhile, in OUMS-27 cells (a human chondrosarcoma cell line), both TNF-α, IL-1β, and IL-6 could upregulate KIAA1199 expression." (PMID 37569797, 2023). "In addition, RIAA inhibited NF-κB-mediated inflammatory markers in various cell models, including nitric oxide in LPS-stimulated RAW 264.7 cells, RANKL-mediated TRAP activity in transformed osteoclasts, and TNF-α/IL-1β-mediated MMP-13 expression in SW1353 human chondrosarcoma cells." (PMID 19712471, 2009). "Our results showed that NUC1 treatment inhibited the extracellular release of MMPs by blocking TNF-α-induced MMP-1, MMP-3, and MMP-13 expression in chondrosarcoma cells." (PMID 37482815, 2023). "We first verified that transcriptional expression of MMP1, MMP3, MMP13, and ADAMTS4 was upregulated by IL-1β or TNF-α and repressed by I-BET151 in a human chondrosarcoma cell line (SW1353)." (PMID 30786900, 2019). "Though PI3/Akt signalling pathway can be activated by TNF-α in human smooth muscle cells or IL-1β in rat brain astrocytes, our results are consistent with BDNF-induced migration in human chondrosarcoma through a transducing signal involving TrkB." (PMID 25418464, 2014).
chronic lung disease (20 papers, 2011 to 2025). According to the definitions of the American and British Thoracic Societies, including pulmonary functional tests, X-rays, and CT scans for items such as fibrosis, bronchiectasis, bullae, emphysema, nodular or lymphomatous abnormalities. "Emerging at-risk populations include those with chronic lung disease (patients receiving steroids and TNF antagonists) and traumatic injuries." (PMID 34188199, 2021). "Finally, the broader implications of this research highlight the potential connections between TNF-α polymorphisms and chronic lung diseases, reinforcing the need for continuous exploration of genetic factors that affect the respiratory health of premature infants." (PMID 39748810, 2024). "Locally produced TSG-6 may be essential for HC-HA formation in various lung compartments during bacterial or other types of inflammation associated with high TNFα levels, a cytokine implicated in the pathogenesis of a variety of acute and chronic lung diseases in humans." (PMID 29855321, 2018). "Inflammatory biomarkers, such as C-reactive protein (CRP), interleukins 1 and 6 (IL-1 and IL-6), and tumor necrosis factor-alpha (TNF-α) have all been reported to be increased in the circulation of the elderly and patients with chronic lung disease." (PMID 40729030, 2025). "We investigated the effects of IL-17A plus TNF-α, 2 cytokines with relevant roles in CF and other chronic lung diseases." (PMID 36219481, 2022). "Previous reports have described the inhibitory properties of peptide Ac2-26 in models of chronic lung disease, a phenomenon accounted for by the suppression of profibrotic cytokine production including TNF-α and TGF-β." (PMID 35269381, 2022). "For chronic lung disease, the mir-132-3p was significantly upregulated in smokers, thus inducing increased concentrations of inflammatory cytokines (interleukin-1β and tumor necrosis factor-α)." (PMID 34796198, 2021). "It is well known that the expression and secretion of MMP-9 in chronic lung diseases is regulated by various stimuli, including IL-1β, TNF-α, and LPSs." (PMID 32829707, 2020). "This validates AMs to be the main early airway TNF-α source following pneumococcal stimulation and, more importantly, suggests a functional impairment of AMs in chronic lung disease." (PMID 26319657, 2015). "On the other hand, circadian clock disruption during chronic lung diseases has essential effect in augmented oxidative stress and increased systemic inflammation, as evidenced by increased interleukin-6, C-reactive protein, and tumor necrosis factor." (PMID 38225649, 2024). "We have shown that these cells produce increased cytotoxic (granzyme b and perforin) and inflammatory (IFNγ and TNFα) mediators in several adult chronic lung diseases and hypothesised that similar changes would be evident in children with BE." (PMID 26258716, 2015). "Furthermore, published studies have suggested that the release of inflammatory cytokines involving IL-1β, IL-6, and TNF-α participated in activating p38 MAPK and JNK signaling pathways in chronic lung diseases." (PMID 35754478, 2022).